GRM7 (glutamate metabotropic receptor 7)
Diseases named in the same sentence as GRM7 in open-access papers (continued):
Sharing a sentence is not in itself a finding about the gene and the disease.
Obesity (4 papers, 2010 to 2025). Accumulation of substantial excess body fat. "Among those, the genes encoding the neuropeptide Y (NPY), two glutamate receptors (GRIK1, GRM7), the X-linked gastrin-peptide receptor (GRPR), and the organic anion transporter (SLCO4C1) are novel obesity candidate genes that may contribute to highly penetrant forms of familial obesity." (PMID 28489853, 2017). "A total of 10 shared co-expressed partners were identified in the analysis between our 4 novel strongest candidate genes (GRIK1, GRM7, GRPR and SLCO4C1) and the set of 15 obesity-related genes described in the literature." (PMID 28489853, 2017). "To further assess the possible implication of these strong candidate genes (GRIK1, GRM7, GRPR and SLCO4C1), we determined the co-expression patterns between them and 15 well-defined genes from the leptin-melanocortin pathway previously related to obesity." (PMID 28489853, 2017).
nicotine dependence (3 papers, 2012 to 2018). Physical and psychological dependence on nicotine. "Both GRM7 and GRM8 are part of the glutamate signaling pathway and were previously reported to be associated with nicotine dependence and smoking initiation respectively." (PMID 23227220, 2012). "For example, GRM7 in chromosome 3p26.1 and GRM8 in chromosome 7q31.33 are important in the biological processes and development of nicotine dependence, and some of these risks may be shared across diverse population." (PMID 30104567, 2018).
Rett syndrome (3 papers, 2018 to 2026). A severe neurodevelopmental disorder affecting the central nervous system. "Other hub genes (GABBR2, GRM7, MEF2C, SCN2A, KMT2C, and DAGLA) dysfunction have been reported to contribute to ASD and other psychiatric disorders such as Attention-Deficit Hyperactivity Disorder (ADHD), Huntington’s disease, and Rett-syndrome." (PMID 31649562, 2019).
breast carcinoma (2 papers, 2010 to 2018). "GRM7 has been reported to be hypermethylated in breast cancer cells." (PMID 30124166, 2018).
Cerebral atrophy (2 papers, 2020 to 2021). Atrophy (wasting, decrease in size of cells or tissue) affecting the cerebrum. "Detailed clinical characterization of 11 individuals from six unrelated families demonstrates that rare biallelic GRM7 pathogenic variants can cause DEEs, microcephaly, hypomyelination, and cerebral atrophy." (PMID 32286009, 2020). "We show here that rare biallelic variants in GRM7 cause a severe neurological phenotype characterized by microcephaly, DEE, hypomyelination, and cerebral atrophy." (PMID 32286009, 2020). "Overall, the findings of both congenital neuroimaging features such as under‐opercularization and thin corpus callosum and progressive features such as cerebral atrophy suggest that GRM7‐related disorders are both congenital and progressive in nature similar to that seen in GRIA2‐related NDDs." (PMID 32286009, 2020). "We comprehensively characterized the clinical features and variants in six families with biallelic variants in GRM7 and showed that rare GRM7 biallelic variants can cause a severe neurological phenotype characterized by microcephaly, DEE, hypomyelination, and cerebral atrophy." (PMID 32286009, 2020).
Tinnitus (2 papers, 2017 to 2021). Tinnitus is an auditory perception that can be described as the experience of sound, in the ear or in the head, in the absence of external acoustic stimulation. "Our data suggests that allele A/T of GRM7 can have a statistically significant influence toward the severity of tinnitus." (PMID 29163129, 2017). "We found relevant statistical association between the presence of the allele A/T of GRM7 and severe tinnitus." (PMID 29163129, 2017). "In addition, the severity of tinnitus and the GRM7 genotype were associated, and the percentage of patients with the A/T genotype was high in the severe tinnitus group." (PMID 34205595, 2021). "Association between THI score (tinnitus severity) and GRM7 gene." (PMID 29163129, 2017). "The relation between tinnitus and GRM7 gene was evaluated considering two groups, one defined as “having an A allele” (AA + AT) other defined as “not having an A allele” (TT)." (PMID 29163129, 2017). "This is the first study evaluating the effect of GRM7 and NAT2 gene in tinnitus." (PMID 29163129, 2017). "No other studies were found relating GRM7, NAT2 and tinnitus." (PMID 29163129, 2017).
acute myeloid leukemia (1 paper, 2025). Acute myeloid leukemia (AML) is a group of neoplasms arising from precursor cells committed to the myeloid cell-line differentiation. "We found that zinc finger protein 668 (ZNF668), eosinophil granule ontogeny transcript (EGOT), and glutamate metabotropic receptor 7 (GRM7) could serve as novel biomarkers for acute myeloid leukemia (LMAL)." (PMID 40699783, 2025).
bladder cancer (1 paper, 2025). "In cisplatin-resistant bladder cancer cell lines, FLRT2, HOXC5, SCD, GRM7, HMGA1, ETV7, and SCO2 were highly expressed, while EMP1, SERPINA6, and ZNF124 exhibited lower expression levels." (PMID 39744172, 2025).
cervix cancer (1 paper, 2022). "In cervix cancer, the mutation of glutamate receptor, metabotropic 7 (GRM7) gene can increase the expression of YY1." (PMID 35791393, 2022).
cocaine addiction (1 paper, 2025). "After pointing out the involvement of mGlurs in cocaine addiction and the identification of Grm7 as a gene modulating alcohol drinking, relapse to drug seeking was also investigated." (PMID 40149928, 2025).
colon cancer (1 paper, 2013). "Among the group of the most consistently hypermethylated genes in both human colon cancer and mouse intestinal adenoma (48 genes), we found Cdh4, Crabp1, Crmp1, Dbc1, Duox1, Grm7, Hand1, Hs3st2, Pcdh17 and Pdpn, which have previously been suggested as cancer biomarkers." (PMID 23408899, 2013).
endometrial carcinoma (1 paper, 2021). A malignant tumor arising from the epithelium that lines the cavity of the uterine body. "Of these somatic mutations of APLP2 and ARGHEF12 have been detected in head-and-neck SCC and cervical SCC respectively, and that of GRM7 and GALNACT have been detected in endometrial carcinoma." (PMID 34298793, 2021).
Epileptic encephalopathy (1 paper, 2021). A condition in which epileptiform abnormalities are believed to contribute to the progressive disturbance in cerebral function. "In conclusion, we identified a novel homozygous missense mutation c.1411G>A (p.Gly471Arg) in the GRM7 gene segregating with the disease in a large consanguineous Tunisian family comprising several cases of developmental and epileptic encephalopathy." (PMID 34273994, 2021). "We describe the identification of a novel homozygous c.1411G>A (p.Gly471Arg) variant in the GRM7 gene in a large Tunisian consanguineous family diagnosed with developmental and epileptic encephalopathies (DEE)." (PMID 34273994, 2021).
glioblastoma (1 paper, 2025). The most malignant astrocytic tumor (WHO grade IV). "The glutamate receptor 7 (GRM7) is proposed to predict prognosis in head and neck cancers as well as glioblastomas 36010616, 35626148." (PMID 39744172, 2025).
Hypertension (1 paper, 2016). The presence of chronic increased pressure in the systemic arterial system. "Several gene regions identified in this study were near previously implicated hypertension genes (eg, GRM7, SLC4A7, ADAMTS9)." (PMID 26866891, 2016). "However, generalization of previously implicated hypertension (GRM7, SLC4A7, ADAMTS9) and SBP-associated loci (PLEKHA7) from cross-sectional analyses with much larger sample sizes, provide strong evidence that these statistical models are robust." (PMID 26866891, 2016).
lipodystrophy (1 paper, 2022). A congenital or acquired disorder characterized by abnormal loss or redistribution of the adipose tissue in the body. "In HP lipodystrophy, the pancreatic SCG5-low donors had stronger and more correlations among lipodystrophy genes than pancreatic SCG5-high donors, and positive correlation between GRM7 and SYNBE1 was stronger in pancreatic SCG5-high donors than SCG5-low donors." (PMID 36059698, 2022).
migraine (1 paper, 2015). "Collectively, association of variants in these neurotransmitter-related genes ADARB2; GRM7; HTR7 connected by a common neurological pathway supports current theories of a perturbed serotonin and glutamate mechanism in migraine and in the Norfolk pedigree." (PMID 25916332, 2015). "In addition to ADARB2 SNPs, the Norfolk Island pGWAS also found two SNPs in the glutamate receptor, metabotropic 7 (GRM7) gene and one SNP in the 5-hydroxytryptamine serotonin receptor 7 adenylate cyclase-coupled (HTR7) gene to be associated with migraine." (PMID 25916332, 2015).
neuroblastoma (1 paper, 2023). Neuroblastoma (NB) is the most common solid, extracranial childhood tumor. "It should be noted that GRM2, GRM7 and GRM8 are the mGluR genes that showed the highest expression values in our SK-N-SH cells, which is in accordance with data reported in SH-SY5Y neuroblastoma cells." (PMID 36768378, 2023).
parasitic infection (1 paper, 2020). "Genetic variants of interest identified in several immune related genes for all the antibody response and parasitic infection traits: IBDV (TOLLIP, ANGPTL5, BCL9, THEMIS2), MDV (GRM7), SG (MAP3K21), Eimeria (TOM1L1), and cestodes (TNFAIP1, ATG9A, NOS2)." (PMID 33193617, 2020).
sensorineural hearing loss (1 paper, 2019). "While there have been many published reports associating glutamate metabotropic receptor 7 with sensorineural hearing loss, there is no report, till date, about the association of glutamate metabotropic receptor 7 polymorphisms with sensorineural hearing loss at different ages." (PMID 30528655, 2019).
neurodevelopmental disorder (11 papers, 2018 to 2025). A behavioral and cognitive disorder with onset during the developmental period that involves impaired or aberrant development of intellectual, motor, or social functions. "GRM7 is known to regulate neurotransmission and mutations in this gene that result in reduced expression have been linked to neurodevelopmental disorders, suggesting GRM7 is a disease-causing gene." (PMID 40656995, 2025). "Further research has revealed that pathogenic mutations in GRM7, associated with neurodevelopmental disorders, impair axon outgrowth and the development of presynaptic terminals." (PMID 40149928, 2025). "Supporting a role of GRM7 in human neurodevelopmental disorders (NDD-s), studies on genetically targeted and Grm7-variant mice have reported symptoms similar to clinical symptoms (see Section 4.2." (PMID 40149928, 2025). "Among these, haploinsufficiency ofSETD5, BRPF1, CRBN, ATG7, SLC6A11, GRM7, and ARPC4has been linked to neurodevelopmental disorders and cognitiveimpairment." (PMID 40995453, 2025). "Taken together with the fact that Grm7 knockout mice recapitulate phenotypes often observed in neurodevelopmental disorders, it was likely that GRM7 clinical variants would lead to loss-of-function of the mGlu7 receptor." (PMID 33476302, 2021). "In recent years, whole exome sequencing (WES) studies have identified rare deletions and variants in GRM7, the human gene encoding mGlu7, in patients with neurodevelopmental disorders." (PMID 33476302, 2021). "Grm7, as the G-protein coupled receptor activated by glutamate, is related to neurodevelopmental disorders." (PMID 35268596, 2022). "We previously proposed GRM7 as a candidate disease gene in two families with neurodevelopmental disorders (NDDs)." (PMID 32286009, 2020).
cancer (5 papers, 2013 to 2025). A tumor composed of atypical neoplastic, often pleomorphic cells that invade other tissues. "Studies of benign and tumor prostate samples from African American men show the differential methylation of GRM7, which is significantly associated with cancer progression." (PMID 40149928, 2025). "Genetic studies of samples from several forms of cancer recognize GRM7 as one of the contributing genes." (PMID 40149928, 2025). "Given the role of these pathways in cancers, we speculated that GRM1, GRM2 and GRM7 may be associated with DIPG progression by involving in these pathways." (PMID 30124166, 2018). "Meanwhile, some proteins act as known oncogenes in most cancers except LAML, such as ZNF668 and GRM7." (PMID 40699783, 2025).
tumor (4 papers, 2016 to 2025). "The expression of mGluR1 (GRM1) and mGluR5 (GRM5) was conserved from primary tumours to metastatic samples, but moderate changes were evident for other receptors such as mGluR2/3/7/8 (GRM2, GRM3, GRM7, and GRM8)." (PMID 37173906, 2023). "Genes specifically lost in tumour samples with high NCS include KIAA1644, TAMM41, GRM7, TTC39B and FREM1." (PMID 35326573, 2022).
GRM7 also shares sentences with these, for which no sentence is quoted: Parkinson disease (5 papers); neurological disorders (4); anxiety disorder (3); autism spectrum disorder (3); Intellectual disability (3); mood disorder (3); psychosis (3); Alzheimer disease (2); anaphylaxis (2); diabetes (2); Huntington disease (2); microcephaly (2); neuropathic pain (2); psychiatric disorder (2); alcohol addiction (1); alcohol dependence (1); alcohol use disorder (1); bladder tumor (1); Brain atrophy (1); brain injury (1); Cognitive impairment (1); coronavirus disease 2019 (1); cortical atrophy (1); developmental and epileptic encephalopathy (1); head and neck cancer (1); hearing disorder (1); Metabolic Disorder (1); Pain (1); phobia (1); post-traumatic stress disorder (1).
A further 3 diseases each share a sentence with GRM7 in 1 paper.